LINC00941 (long intergenic non-protein coding RNA 941 )
Synonyms: LISRR; lncIAPF; lncRNA-MUF; LOC645485
Gene: Long non-coding RNA gene on chromosome 12 (30,755,074 to 30,881,888, forward strand). Ensembl gene ENSG00000285517.
Diseases named in the same sentence as LINC00941 in open-access papers:
LINC00941 is named in the same sentence as 31 diseases in open-access papers, as found by Europe PMC text mining. Sharing a sentence is not in itself a finding about the gene and the disease. The quoted sentences say what the papers report.
pancreatic cancer (16 papers, 2021 to 2025). "In TCGA data analysis, the high expression of LINC00941 was associated with poor prognosis of patients with pancreatic cancer." (PMID 36612299, 2023). "In this study, we prove that the expression of LINC00941 is tightly associated with MAPK activity in pancreatic cancer cells." (PMID 36612299, 2023). "TCGA data analysis indicated that high expression of LINC00941 was associated with poor prognosis of pancreatic cancer patients." (PMID 36612299, 2023). "Moreover, TCGA data analysis indicated that high expression of LINC00941 was associated with poor prognosis of patients with pancreatic cancer." (PMID 36612299, 2023). "In PC, LINC00941 expression was found to be higher in pancreatic cancer tissues, and its localization was primarily observed in the cytosol of tumor cells." (PMID 38370364, 2024). "Next, wound healing and Transwell assays were performed to reveal the role of LINC00941 in the metastasis of pancreatic cancer." (PMID 37215454, 2023). "In vivo studies demonstrated that knockout of LINC00941 the inhibited metastasis of pancreatic cancer." (PMID 37215454, 2023). "Recent studies have demonstrated that LINC00941 is involved in tumorigenesis and malignant phenotypes of several kinds of cancers, including pancreatic cancer." (PMID 36612299, 2023). "Among them, LINC00941 was consistently promoted by MAPK in the examined pancreatic cancer cell lines." (PMID 36612299, 2023). "We determined that LINC00941 was commonly promoted by MAPK in the examined pancreatic cancer cell lines." (PMID 36612299, 2023). "For instance, LINC00941 has been indicated to accelerate glycolysis in pancreatic cancer by activating the Hippo pathway." (PMID 37215454, 2023). "We discovered that in pancreatic cancer, LINC00941 acts as a protein decoy in the cytoplasm and confirmed that it can competitively bind to the E3 ubiquitin ligase NEDD4L to inhibit the ubiquitination of ANXA2 and promote its stabilization." (PMID 35977942, 2022). "A recent study has reported that LINC00941 plays a vital role in inhibiting cell proliferation of pancreatic cancer cells." (PMID 36034461, 2022). "LINC00941 promotes the progression of pancreatic cancer by regulating the Hippo pathway and promoting glycolysis in pancreatic cancer cells." (PMID 35647035, 2022). "CASC8, DNMBP-AS1, LINC00941, TM4SF1-AS1, and UCA1 expression was positively correlated with risk scores, indicating that they are risk factors for pancreatic cancer; in contrast, SNHG10 and SOCS2-AS1 were negatively correlated, thus serving as protective factors for pancreatic cancer." (PMID 36871072, 2023). "The ceRNA role of LINC00941 was also reported in pancreatic cancer and hepatocellular carcinoma." (PMID 36717549, 2023). "Therefore, LINC00941 is indicated as one of the major onco-lncRNAs in various cancers, including pancreatic cancer." (PMID 36612299, 2023). "To determine the functional significance of LINC00941 in pancreatic cancer, we examined whether cellular proliferation is altered by altering the expression of LINC00941 in cultured pancreatic cancer cells." (PMID 36612299, 2023). "For example, LINC00941 is abnormally upregulated in pancreatic cancer, promoting glycolysis by regulating the Hippo pathway, thereby promoting the malignant biological behavior of pancreatic cancer." (PMID 35087800, 2021). "Additionally, LINC00941 may promote the proliferation of pancreatic cancer cells, leading to metastasis through competitive binding with miR-873-3p41." (PMID 36871072, 2023). "Further screening identified five pancreatic cancer-specific epi-lncRNA genes (AL161431.1, LINC00663, LINC00941, SNHG10, and TM4SF1-AS1), which were used to construct a prognostic model." (PMID 40264765, 2025). "For example, LINC00941 activates Hippo pathway through interacting with MST1 and subsequently enhances glycolysis in pancreatic cancer." (PMID 36717549, 2023).
pancreatic cancer (continued). "The results showed that AL161431.1, LINC00663, LINC00941, and SNHG10 were highly expressed in pancreatic cancers samples; in particular, AL161431.1 and LINC00663 had significantly higher levels." (PMID 35647035, 2022). "AL161431.1, LINC00663, LINC00941, and SNHG10 expressions in pancreatic cancer cells were relatively higher as compared to the normal cells." (PMID 35647035, 2022). "Survival analysis of pancreatic cancer samples showed that low expression of UCA1, TM4SF1-AS1, LINC00941, DNMBP-AS1, and CASC8 improved OS more than high expression, whereas high expression of SNHG10 and SOCS2-AS1 improved OS more than low expression (P < 0.001)." (PMID 36871072, 2023). "The RT-PCR result confirmed that AL161431.1, LINC00663, LINC00941, and SNHG10 expressions in pancreatic cancer samples were higher as compared to normal pancreatic samples; the expression of TM4SF1-AS1 in pancreatic cancer cells was significantly lower than that in normal pancreatic samples." (PMID 35647035, 2022).
gastric cancer (10 papers, 2020 to 2024). A primary or metastatic malignant neoplasm involving the stomach. "LINC00941 was first identified in gastric cancer, where its elevated expression was associated with invasion depth, lymphatic metastasis, and TNM stage." (PMID 33414429, 2021). "LINC00941 has been found to mediate the development of gastric cancer, and LINC00941 was negatively associated with the longer overall survival of lung adenocarcinoma patients." (PMID 33869051, 2021). "In this study, we found that similar to gastric cancer, high LINC00941 expression was linked to high OSCC cell proliferation, colony formation and tumour growth in vivo." (PMID 32691935, 2020). "Previous studies showed that, in gastric cancer, aberrant expression of LINC00941 was associated with tumour depth and distant metastasis." (PMID 32691935, 2020). "LINC00941-knock-down experiments reduced gastric cancer cell proliferation and migration in vitro as well as tumor growth in mice." (PMID 36869839, 2023). "In gastric cancer, the expression of LINC00941 is increased, which provides a bad prognosis as well as encourages proliferation and metastasis." (PMID 34764994, 2021). "LINC00941 has been found to mediate the development of gastric cancer, head and neck squamous cell carcinoma, and papillary thyroid cancer." (PMID 33869051, 2021). "LINC00941 has been reported to be associated with pro-tumorigenic and pro-metastatic behaviors during tumorigenesis, such as colorectal cancer (CRC) and gastric cancer." (PMID 34532296, 2021). "Silencing of LINC00941 greatly inhibited gastric cancer cell proliferation, migration and invasion in vitro and modulates tumour growth in vivo." (PMID 32691935, 2020). "LINC00941 expression has shown to be positively correlated with gastric cancer progression." (PMID 36869839, 2023). "Overexpression of LINC00941 promoted the progression of gastric cancer (GC) via regulating cancer-related biological processes." (PMID 36717549, 2023).
lung adenocarcinoma (8 papers, 2018 to 2024). A carcinoma that arises from the lung and is characterized by the presence of malignant glandular epithelial cells. "The expression of LINC00941 was elevated in lung adenocarcinoma (LUAD) and associated with phosphorylation of the PI3K-AKT signaling pathway." (PMID 36717549, 2023). "In lung adenocarcinoma, survival of patients was negatively associated with high expression of LINC00941 which modulates focal adhesion and PI3K-AKT signaling pathway." (PMID 30723491, 2019). "Moreover, LINC00941 was negatively associated with the longer overall survival of lung adenocarcinoma patients." (PMID 33869051, 2021). "Using RT‐qPCR analysis, we confirmed the upregulation of LINC00941 in tumour tissues and cell lines of human lung adenocarcinoma (LUAD)." (PMID 39392103, 2024). "LINC00941 expression has been used to successfully predict the survival of patients with lung adenocarcinoma (LAD) and was identified as a biomarker for hypoxia, which is associated with reduced survival of LAD patients." (PMID 36869839, 2023). "Previous studies have shown that LINC00941, also called MSC upregulated factor (lncRNA-MUF), was negatively associated with OS and phosphorylation of the PI3K/AKT signaling pathway in lung adenocarcinoma patients." (PMID 36118862, 2022). "Correlation analysis using ENCORI website showed that there was a negative correlation between LINC00941 and miR-877-3p in lung adenocarcinoma (LUAD)." (PMID 33869051, 2021). "LINC00941 was first found in lung adenocarcinoma (LUAD), and lung adenocarcinoma belongs to NSCLC." (PMID 33869051, 2021).
hepatocellular carcinoma (7 papers, 2019 to 2024). A malignant tumor that arises from hepatocytes. "Upregulation of LINC00941 has also been observed in patients with hepatocellular carcinoma (HCC) and has been implicated in HCC relapse." (PMID 36869839, 2023). "In hepatocellular carcinoma, high expressed LINC00941 significantly promoted epithelial to mesenchymal transition (EMT) and malignant capacity." (PMID 30723491, 2019). "In hepatocellular carcinoma, high expression of LINC00941 significantly promoted EMT and malignant capacity tissues and correlated with poor prognosis." (PMID 30723491, 2019). "Another study also found that depletion of LINC00941 inhibited EMT and activated Wnt/ß-catenin signaling in hepatocellular carcinoma." (PMID 36118862, 2022).
colon cancer (6 papers, 2019 to 2023). "LINC00941 is upregulated in colon cancer and was shown to sponge miR-205-5p, leading to increased expression of MYC." (PMID 36869839, 2023). "In this study, some of the DEirlncRNAs in the process of modeling that have been already identified play an important role in malignant phenotypes of various cancer types, such as SNHG22, PRR7-AS1, and LINC00941, especially for colon cancer, while others were revealed for the first time." (PMID 35249533, 2022). "In addition, linc00941 was found to be up-regulated in the colon cancer cells." (PMID 34254950, 2021). "LINC00941 can regulate MYC expression by directly interacting with miR-205-5p, and LINC00941 overexpression promotes the proliferation, migration, and invasion ability of colon cancer cells." (PMID 38002356, 2023). "LINC00941 was differentially expressed in TGF-β1-activated A549 cells compared with those in normal controls and was up-regulated upon treatment of colon cancer cells with chemotherapeutic drugs." (PMID 30723491, 2019).
oral squamous cell carcinoma (6 papers, 2020 to 2024). "LINC00941 is upregulated in oral squamous cell carcinoma (OSCC) and was shown to induce epithelial-to-mesenchymal transition (EMT) in vitro by associating with the heterogeneous nuclear ribonucleoprotein K (hnRNPK)." (PMID 36869839, 2023). "Under the condition of oral squamous cell carcinoma, EP300 activated LINC00941 transcription through upregulating H3K27ac modification in its promoter." (PMID 34544413, 2021).
pulmonary fibrosis (6 papers, 2022 to 2024). Chronic progressive interstitial lung disorder characterized by the replacement of the lung tissue by connective tissue, leading to progressive dyspnea, respiratory failure, or right heart failure. "Another recent study found that upregulated LINC00941 is associated with idiopathic pulmonary fibrosis (IPF), which is an incurable and progressive disease characterized by lung scarring." (PMID 36869839, 2023). "Recent findings indicate that activating transcription factor 3 (ATF3) can stimulate LINC00941/lncIAPF to promote the differentiation of fibroblasts into myoblasts by inhibiting ELAVL1/HuR-dependent autophagy in pulmonary fibrosis." (PMID 39612365, 2024). "In addition, blocking autophagic flow mediated by linc00941/lncIAPF-ELAVL1/HuR promotes fibroblast differentiation, providing new targets and effective therapeutic strategies for autophagy-based treatments for idiopathic pulmonary fibrosis." (PMID 38365674, 2024).
lung cancer (4 papers, 2021 to 2024). A malignant neoplasm involving the lung. "LINC00941 has also been implicated in non–small cell lung cancer, where it was found to promote angiogenesis and tumor progression by sponging miR-877-3p, which is a negative regulator of VEGFA." (PMID 36869839, 2023). "Moreover, in agreement with the results of tumour tissues, the upregulation of LINC00941 was also observed in four lung cancer cell lines." (PMID 39392103, 2024).
papillary thyroid cancer (4 papers, 2021 to 2023). "In papillary thyroid cancer, it was found that TGF-β induces the transcription of LINC00941, which upregulates CDH6, an oncogene that promotes metastasis and EMT by modulating cytoskeleton adhesions, which hinder autophagy." (PMID 36869839, 2023). "Linc00941 was found to be a novel transforming growth factor beta (TGF-beta) target by recruiting cadherin 6, which subsequently enhanced papillary thyroid carcinoma metastasis." (PMID 34254950, 2021).
esophageal squamous cell carcinoma (3 papers, 2021 to 2023). Esophageal squamous cell carcinoma (ESCC) is a type of esophageal carcinoma (EC) that can affect any part of the esophagus, but is usually located in the upper or middle third. "LINC00941 promotes the progression of esophageal squamous cell carcinoma by regulating PMEPA1 expression as a competitive endogenous RNA of mir-877-3p." (PMID 35647035, 2022). "However, the exact function and relative regulatory mechanism of LINC00941 in carcinogenesis of esophageal squamous cell carcinoma (ESCC) remain to be further clarified." (PMID 36717549, 2023).
glioma (2 papers, 2021 to 2025). A benign or malignant brain and spinal cord tumor that arises from glial cells (astrocytes, oligodendrocytes, ependymal cells). "The inhibition of LINC00941 significantly reduced the proliferation of glioma cells, whereas the inhibition of BASP1-AS1 significantly promoted their proliferation rates (p<0.05)." (PMID 34659218, 2021). "Moreover, the expression of LINC00941 was significantly elevated in grade III glioma than grade II one, whereas that of BASP1-AS1 exhibited opposite expression pattern (p<0.05)." (PMID 34659218, 2021). "Similarly, LINC00941 was highly expressed in IDH wildtype glioma, and BASP1-AS1 was highly expressed in IDH mutant glioma (p<0.05)." (PMID 34659218, 2021). "Moreover, EdU assay revealed that the proliferation of glioma cells was suppressed by the inhibition of LINC00941 and promoted by the inhibition of BASP1-AS1." (PMID 34659218, 2021). "In vitro experiments revealed that the inhibition of LINC00941 could significantly suppress the proliferation of glioma cells, whereas the inhibition of BASP1-AS1 exerted reversed effects." (PMID 34659218, 2021). "Since EMT and TNF-α were found to be highly involved in the progression of glioma, the increased level of LINC00941 and the decreased level of BASP1-AS1 might account for the promoted proliferation of glioma cells through activating EMT and TNF-α signaling pathway." (PMID 34659218, 2021).
liver disease (2 papers, 2022 to 2023). "LINC00941 upregulation has also been observed in patients with other liver diseases such as chronic hepatitis B and cirrhosis." (PMID 36869839, 2023). "Here, we aimed to explore the changes of LINC00941 and LINC00514 expression in hepatitis B virus (HBV) infection‐related liver disease and evaluate their application value in disease diagnosis." (PMID 34825738, 2022). "In this research, we detected the expression of LINC00941 and LINC00514 in healthy controls and patients with HBV infection‐related liver disease and assessed its correlation with basic characteristics of patients with HCC." (PMID 34825738, 2022).
lymph node metastasis (2 papers, 2019 to 2021). "High LINC00941 expression was strongly associated with larger tumor size, lymph node metastasis, and poor prognosis." (PMID 33414429, 2021).
non-small cell lung carcinoma (2 papers, 2021 to 2022). A group of at least three distinct histological types of lung cancer, including non-small cell squamous cell carcinoma, adenocarcinoma, and large cell carcinoma. "LINC00941 regulates VEGFA expression by adsorbing mir-877-3p and promotes the progression of non-small cell lung cancer." (PMID 35647035, 2022).
Cachexia (1 paper, 2021). Severe weight loss, wasting of muscle, loss of appetite, and general debility related to a chronic disease. "In addition, the mice in the control group began to lose weight after 6 weeks of feeding, possibly because they were more prone to cachexia than the mice of the LINC00941 suppression groups." (PMID 33414429, 2021).
esophageal cancer (1 paper, 2023). A primary or metastatic malignant neoplasm involving the esophagus. "The expression level of LINC00941 was significantly increased in esophageal carcinoma tissues compared to normal controls in GEPIA dataset (including 182 ESCA tumor samples and 286 normal controls; P < 0.05)." (PMID 36717549, 2023).
head and neck squamous cell carcinoma (1 paper, 2023). A squamous cell carcinoma that arises from any of the following anatomic sites: lip and oral cavity, nasal cavity, paranasal sinuses, pharynx, larynx, and salivary glands. "LINC00941 is found to be a prognostic biomarker for head and neck squamous cell carcinoma (HNSCC)." (PMID 36869839, 2023).
oral cancer (1 paper, 2020). "In the present study, we demonstrated that LINC00941 promoter H3K27ac modification mediated by EP300 elevated LINC00941 expression in oral cancer cells." (PMID 32691935, 2020).
renal carcinoma (1 paper, 2023). A carcinoma arising from the epithelium of the renal parenchyma or the renal pelvis. "In vitro experiments indicated that LINC00941 can enhance the malignant biological behaviors of renal cancer cells." (PMID 36837389, 2023). "In addition, LINC00941 could enhance the malignant biological behaviors of renal cancer cells." (PMID 36837389, 2023).